HMGB1 (high mobility group box 1)
Diseases named in the same sentence as HMGB1 in open-access papers (continued):
Sharing a sentence is not in itself a finding about the gene and the disease.
type 1 diabetes (20 papers, 2012 to 2025). "In mice with type 1 diabetes, icariin (flavonoid glycoside) produced from the epimedium protects the arteries by lowering inflammation linked to high-mobility group box 1 (HMGB1)." (PMID 41567643, 2025). "In patients with type 1 diabetes, higher levels of plasma HMGB1 are independently associated with a higher risk of all-cause mortality and, to a lesser extent, with a higher incidence of CVD." (PMID 22752054, 2012). "The main findings of this study are that, in patients with type 1 diabetes, and after adjustments for confounders, higher levels of plasma HMGB1 are associated with a higher incidence of all-cause mortality and also, though to a lesser extent, fatal and non-fatal CVD." (PMID 22752054, 2012). "Further, HMGB1 had translocated from the nucleus into the cytoplasm in both the autoantibody-positive and type 1 diabetes donor islets when compared with control donors." (PMID 37558746, 2023). "Induction of Treg by HMGB1 is also reported in type 1 diabetes and psoriasis vulgaris, an autoimmune inflammatory skin disease." (PMID 35150340, 2022). "By using an experimental type 1 diabetes mouse model, it has been demonstrated that HMGB1 maintains inflammation via modulation of RAGE/AKT1/β-catenin signaling pathway in the diabetic lung." (PMID 34008469, 2021). "In summary, we have provided strong evidence indicating the involvement of HMGB1 in type 1 diabetes pathogenesis." (PMID 32072192, 2020). "In the current report, we employed NOD mice as a model to dissect the impact of blocking HMGB1 on the prevention, treatment and reversal of type 1 diabetes." (PMID 32072192, 2020). "To explore the relevance of our data to human type 1 diabetes, we used ELISA to determine the concentration of plasma HMGB1 in 34 healthy control participants and 30 participants diagnosed with type 1 diabetes within a year." (PMID 32072192, 2020). "Resveratrol, an antioxidant compound in red wine and vegetable foods, has been shown to prevent morphofunctional ventricular remodeling and attenuated HMGB-1 expression in type 1 diabetic rats." (PMID 27847406, 2016). "It has been demonstrated that insulin infusion suppressed HMGB-1/TLRs in monocytes of type 1 diabetes patients." (PMID 27847406, 2016). "The present results also indicated that HMGB1 expression increased in the DRG of STZ-induced type 1 diabetes, rat model, and this finding is consistent with previous reports." (PMID 27216039, 2016). "To examine the role of HMGB1 in myocardial apoptosis in vivo, we induced type 1 diabetes by STZ in mice." (PMID 25210949, 2014). "Clinical and experimental evidence also suggest a role for HMGB1 in the pathogenesis of type I diabetes." (PMID 23772226, 2013). "This study aimed to investigate the associations of plasma levels of the pro-inflammatory cytokine high-mobility group box 1 (HMGB1) with incident cardiovascular disease (CVD) and all-cause mortality in patients with type 1 diabetes." (PMID 22752054, 2012). "In the α cells, the RAGE ligand, CML which is an advanced glycation end product (AGE) was also increased in islets from donors with type 1 diabetes (vs. remaining donor groups), whereas HMGB1 staining intensity was reduced in both autoantibody-positive and type 1 diabetes donors (vs. control)." (PMID 37558746, 2023). "Finally, we found that high circulating levels of HMGB1 in human participants with type 1 diabetes contribute to Treg instability, which paves the way for its use in clinical settings." (PMID 32072192, 2020). "In the current study, we want to determine the prophylactic and therapeutic efficacy of HMGB1-neutralising antibody at different stages of type 1 diabetes, including reversal of disease and protection of islet isografts from recurrent autoimmune attack, and dissect the underlying mechanisms." (PMID 32072192, 2020).
type 1 diabetes (continued). "Whereas, sodium butyrate, as a direct HMGB1 antagonist, could down-regulate the expression of HMGB1 and mediate the balance of Th1/Th2/Th17 paradigm, thus attenuating type 1 diabetes." (PMID 30410469, 2018). "In conclusion, higher levels of plasma HMGB1 may play a role in the development of CVD and high mortality risk in type 1 diabetes and may constitute a specific target for treatment in these patients." (PMID 22752054, 2012). "Indeed, high circulating levels of HMGB1 in human participants with type 1 diabetes contribute to Treg instability, suggesting that blockade of HMGB1 could be an effective therapy against type 1 diabetes in clinical settings." (PMID 32072192, 2020). "In the type 1 diabetes model, streptozotocin (STZ) is a widely used diabetogenic agent, Previous studies have shown that HMGB1 is activated and the expression is increased in STZ-induced diabetic mice." (PMID 30410469, 2018). "The pathways related to the Th1 response (HMGB1 Signaling, Neuroinflammation Signaling pathway, TREM1 Signaling, MIF-mediated Glucocorticoid Regulation, Dendritic Cell Maturation, and Type I Diabetes Mellitus Signaling) were activated at 6, 12 and 24 h after M. avium infection." (PMID 33520738, 2020).
cystic fibrosis (19 papers, 2013 to 2025). Autosomal recessive disorder caused by pathogenic variants in the CFTR gene (cystic fibrosis transmembrane conductance regulator), which encodes a chloride and bicarbonate channel expressed in epithelial cells, and follow the diagnosis criteria. "Pseudomonas aeruginosa cause neutrophilic lung inflammation in cystic fibrosis patients, who express high HMGB1 levels in bronchoalveolar lavage fluid." (PMID 32380958, 2020). "Nevertheless, a reduction of HMGB1 expression was also found in an epithelial bronchial cell model for cystic fibrosis, after in vitro insulin exposure." (PMID 37256493, 2023). "HMGB1 is significantly elevated during Pseudomonas aeruginosa infections and has a clinical relevance in respiratory diseases such as Cystic Fibrosis." (PMID 36071400, 2022). "Systemic treatment with anti-HMGB1 mAb in a preclinical cystic fibrosis model conferred significant protection against P. aeruginosa-induced neutrophil recruitment, protein leak, and lung injury." (PMID 32380958, 2020). "High levels of airway HMGB1 have been reported in patients with cystic fibrosis and in patients on ventilators." (PMID 33126860, 2020). "HMGB1 is an alarmin released from macrophages after infection or inflammation and is a biomarker of lung disease progression in patients with cystic fibrosis." (PMID 28589151, 2017). "Available information is insufficient to understand whether this could be due to inflammation being a stronger driver on HMGB1 levels in cystic fibrosis or if there may be a different regulation in PCOS." (PMID 37256493, 2023). "Furthermore, HMGB1-compromised macrophage functions can result in decreased host defenses against bacterial infection in animal models of cystic fibrosis and VAP." (PMID 33126860, 2020). "Here, we investigated the role of airway epithelium-specific HMGB1 in the pathogenesis of muco-obstructive lung disease in Scnn1b-transgenic (Tg+) mouse, a model of human cystic fibrosis -like lung disease." (PMID 36741411, 2022). "HMGB1 levels are upregulated in the sputum and bronchoalveolar lavage fluid (BALF) of CF patients and cystic fibrosis mice models." (PMID 36741411, 2022). "Interesting data on the role of HMGB1 and IL-33 have also emerged in the context of different respiratory diseases, such as disorders derived from respiratory syncytial virus (RSV) infection and cystic fibrosis." (PMID 36675299, 2023).
status epilepticus (19 papers, 2011 to 2025). Status epilepticus is defined as a continuous seizure lasting more than 30 min, or two or more seizures without full recovery of consciousness between any of them. "The neutralization of HMGB1 by anti-HMGB1 mAb significantly suppressed the acute status epilepticus-caused astrocytes and microglia cells activation." (PMID 28446773, 2017). "Moreover, a status epilepticus-associated increase in HMGB1 has been reported in various other models in rats and mice." (PMID 31959173, 2020). "HMGB1 nucleus-to-cytoplasm translocation has been shown to maintain status epilepticus and drug-resistant temporal lobe epilepsy by mediating oxidative stress in brain tissue in neurons and glial cells." (PMID 39876842, 2024). "Extracellularly released HMGB1 has been revealed to translocate into elongated mitochondria and mediate status epilepticus (SE)-induced CA1 neuronal damage." (PMID 39682695, 2024). "In acute stage of status epilepticus, intravenous therapy with neutralizing anti-HMGB1 monoclonal antibody exhibited neuroprotective effect on neuronal death, inhibition of HMGB1 release, blood brain barrier (BBB) protection and anti-inflammatory actions." (PMID 36310854, 2022). "Many experiments have been done by using animal models to observe involvement of HMGB1 in status epilepticus." (PMID 36310854, 2022). "The anti-inflammatory drug celecoxib (an inhibitor of the cyclooxygenase 2 and HMGB1/TLR-4 pathways) has been documented to significantly reduce the remote consequences of status epilepticus in rats." (PMID 34575901, 2021). "Increased plasma levels of high-mobility group box 1 protein have been reported after unilateral hippocampal electrical stimulation-induced status epilepticus." (PMID 34827090, 2021). "Baram’s group reported that HMGB1 translocation occurred in the amygdala and hippocampus during experimental febrile status epilepticus." (PMID 33321691, 2020). "In agreement, in vivo HMGB-1 blockage with glycyrrhizin, immediately after pilocarpine-induced status epilepticus (SE), reduced neuronal degeneration, reactive astrogliosis and microgliosis in the long term." (PMID 31507379, 2019). "Acute status epilepticus led to a significant reduction of the amount of HMGB1 in the cerebrum due to the HMGB1 translocation." (PMID 28446773, 2017). "Recently, we have reported that up-regulation of LIM kinase 2 (LIMK2) expression induces HMGB1 export from neuronal nuclei during status epilepticus (SE)-induced programmed neuronal necrosis in the rat hippocampus." (PMID 27147971, 2016). "Our patients with intractable epilepsy experiencing status epilepticus attacks also showed high IL-1β, IL-6 and HMGB1 levels." (PMID 21989210, 2011). "The mean HMGB1 level in the serum of afebrile controls was 9.0 ng/mL, that in febrile control was 24.8 ng/mL, and that in afebrile status epilepticus attacks in intractable epilepsy patients was 30.1 ng/mL." (PMID 21989210, 2011). "HMGB1 is a core factor mediating programmed cell death in various cells, and the nucleus-to-cytoplasm translocation of HMGB1 in neurons and glial cells may be an important trigger for status epilepticus." (PMID 39876842, 2024). "Glycyrrhizin can attenuate neuronal damage and alter the disease progression of post-status epilepticus by inhibiting HMGB1 activity and its translocation and protecting the blood–brain barrier permeability in a status epilepticus model induced by lithium-pilocarpine." (PMID 35837232, 2022). "It is worth mentioning that HMGB1 might be involved in P-glycoprotein expression during status epilepticus, which is related to drug resistance." (PMID 33321691, 2020). "In the present study, we focused on whether anti-HMGB1 antibody treatment could relieve status epilepticus- triggered BBB breakdown and inflammation response in addition to the seizure behavior itself." (PMID 28446773, 2017).
status epilepticus (continued). "In addition, the release of disulfide HMGB1 in the brain following status epilepticus may contribute to epileptogenesis and the consequent onset of spontaneous seizures." (PMID 35837232, 2022). "Interestingly, a recent study using a pilocarpine-induced status epilepticus model suggested that nuclear HMGB1 translocation and the subsequent mitochondrial import might deteriorate programmed necrotic neuronal death." (PMID 32155899, 2020). "Experimental studies have shown that the HMGB1 monoclonal antibody can suppress MMP-9 expression and prevent BBB leakage in animal models of status epilepticus." (PMID 40806813, 2025). "A good example is celecoxib, blocking the cyclooxygenase 2 and HMGB1/TLR-4 pathways, which was evaluated in rats surviving lithium-pilocarpine status epilepticus." (PMID 34575901, 2021). "In a recent proteomic study in rats, we have reported an early induction of HMGB1 in the hippocampus and of HSP70 in the hippocampus and parahippocampal cortex as a consequence of an electrically-induced status epilepticus." (PMID 31959173, 2020). "During status epilepticus, HMGB1, a non-histone DNA-binding protein, can be transferred from the cell nucleus to the mitochondria, thereby disrupting the energy metabolism balance of the mitochondria." (PMID 39876842, 2024). "On the other hand, translocation of high mobility group box 1 (HMGB1) and active caspase-3 into mitochondria is involved in apoptosis of parvalbumin (PV) cells (one of the GABAergic interneurons) and necrosis of CA1 neurons in the rat hippocampus, respectively, following status epilepticus (SE)." (PMID 33668863, 2021). "The lack of increased HMGB1 and HSP70 in tissue from dogs with status epilepticus, is in apparent contrast to the experimental findings suggesting relevant species differences." (PMID 31959173, 2020).
thyroid cancer (19 papers, 2015 to 2025). "HMGB1, one of the highly conserved nuclear proteins, is up-regulated in thyroid cancer and associated with clinicopathologic features." (PMID 38679705, 2024). "As HMGB1 is implicated in the progression of thyroid cancer and has been shown to promote aggressive phenotypes in many tumors, we quantified its concentration in EVs and in supernatants from both CAL-62 and BCPAP cells." (PMID 36769076, 2023). "High-frequency ultrasound combined with the detection of serum high mobility group box (HMGB-1), sIL-2R, and thyroglobulin antibody level (TgAb) has diagnostic power in thyroid cancer (sensitivity: 98.0% and specificity: 95.0%)." (PMID 36092957, 2022). "Recent evidence demonstrates that autophagy is associated with NIS expression at the plasma membrane in thyroid cancers and that HMGB1-mediated autophagy could regulate NIS protein degradation." (PMID 33217645, 2021). "In vemurafenib-resistant thyroid cancer cells, elevated HMGB1 suppresses caspase-3 activation and maintains mitochondrial function, reducing drug sensitivity." (PMID 41465435, 2025). "In thyroid cancers, hsa_circ_0062389 (circ0062389) competitively binds to miR-1179, resulting in upregulation of HMGB1 expression, inhibition of E-cadherin protein expression, and enhancing TC metastasis." (PMID 38316961, 2024). "Overexpression of HMGB1 has been shown to reduce the sensitivity of BRAF(V600E) mutant thyroid cancer cells to Vemurafenib by increasing cell viability and decreasing apoptosis and caspase-3 activity." (PMID 39052013, 2024). "In a previous study, we demonstrated that HMGB1, released by thyroid cancer cells, induces over-expression of miR-221/222 and that their overexpression is responsible for PTEN suppression." (PMID 36769076, 2023). "In the thyroid cancer immune network in particular, cytokines such as TGFβ and HMGB1 have been correlated with tumor invasiveness." (PMID 36769076, 2023). "HMGB1 was identified as a critical regulator of autophagy-mediated NIS degradation in differentiated thyroid cancer." (PMID 35846375, 2022). "After a depletion of HMGB1, thyroid cancer cells exhibited fewer autophagosomes as compared with control shRNA group, supporting a critical role of HMGB1 in regulating autophagy." (PMID 31331356, 2019). "Here HBSS treatment induced autophagy of thyroid cancer cells and a targeted deletion of HMGB1 cancelled out this starvation-induced autophagy." (PMID 31331356, 2019). "A pretreatment of NAC in thyroid cancer cells blocked HMGB1 translocation from nucleus into cytosol." (PMID 31331356, 2019). "HMGB1 was over-expressed in thyroid cancer patients’ samples and cell lines and acted as a positive regulator of autophagy." (PMID 31331356, 2019). "Our experimental data also indicated that HMGB1 translocation during autophagy was ROS-dependent in thyroid cancer cells." (PMID 31331356, 2019). "In order to investigate a possible mode of thyroid cancer cell proliferation induced by extracellular HMGB1, expression of miRNA221 and miRNA222 in CAL62 and BCPAP cells was assessed by PCR after addition of HMGB1 for 24, 48, and 72 h." (PMID 26106610, 2015). "Studies have found that HMGB1 expression is significantly up-regulated in Thyroid cancer tissues, and HMGB1 knockout significantly inhibits autophagy, sodium/iodine transporter degradation, and iodine uptake in Thyroid cancer cells treated by starvation induction." (PMID 38577597, 2024). "Furthermore, hsa _circ_0011058 and hsa_circ_0082003 (circ0002111) indirectly promote the translation of angiogenic proteins (VEGFA and FGF) by upregulating YAP1 and HMGB1 in thyroid cancers, respectively, thereby promoting angiogenesis in TCs." (PMID 38316961, 2024). "In conclusion, we report a novel mechanism through which different EMT effectors together with HMGB1 may promote a malignant phenotype in a differentiated and low aggressive thyroid cancer cell line." (PMID 36769076, 2023).